IFIT3 (interferon induced protein with tetratricopeptide repeats 3)
Description:
IFN-induced antiviral protein which acts as an inhibitor of cellular as well as viral processes, cell migration, proliferation, signaling, and viral replication. Enhances MAVS-mediated host antiviral responses by serving as an adapter bridging TBK1 to MAVS which leads to the activation of TBK1 and phosphorylation of IRF3 and phosphorylated IRF3 translocates into nucleus to promote antiviral gene transcription. Exhibits an antiproliferative activity via the up-regulation of cell cycle negative regulators CDKN1A/p21 and CDKN1B/p27. Normally, CDKN1B/p27 turnover is regulated by COPS5, which binds CDKN1B/p27 in the nucleus and exports it to the cytoplasm for ubiquitin-dependent degradation. IFIT3 sequesters COPS5 in the cytoplasm, thereby increasing nuclear CDKN1B/p27 protein levels. Up-regulates CDKN1A/p21 by down-regulating MYC, a repressor of CDKN1A/p21. Can negatively regulate the apoptotic effects of IFIT2.
Synonyms: P60; RIG-G; CIG-49; IFI60; IFIT4; ISG60; GARG-49; IRG2; cig41
Tractability: PROTAC: ubiquitination databases record sites on it; its protein half-life has been measured.
Gene: Protein-coding gene on chromosome 10 (89,327,307 to 89,377,473, forward strand). Ensembl gene ENSG00000119917.
Subcellular location: Cytoplasm; Mitochondrion
Subcellular location (Human Protein Atlas): Cytosol; Mitochondria
Pathways (Reactome):
Immune System: Interferon alpha/beta signaling
Gene Ontology:
Molecular function: identical protein binding; protein binding; RNA binding
Biological process: antiviral innate immune response; negative regulation of apoptotic process; negative regulation of cell population proliferation; response to virus; cellular response to cytokine stimulus; defense response to virus
Cellular component: cytoplasm; cytosol; mitochondrion
Genetic constraint (gnomAD): Loss-of-function variants: 2 observed, 2.8 expected, observed/expected ratio (o/e) 0.71, 90% interval 0.28 to 1.77. That is too few expected variants to judge how well the gene tolerates losing a copy. Missense variants: 481 observed, 592.02 expected, observed/expected ratio (o/e) 0.81, 90% interval 0.75 to 0.88. Synonymous variants: 203 observed, 225.44 expected, observed/expected ratio (o/e) 0.9, 90% interval 0.8 to 1.01.
Homologues: Orthologues: chimpanzee IFIT3 (99% identical), macaque IFIT3 (94% identical), pig IFIT3 (75% identical), rabbit IFIT3 (71% identical), dog IFIT3 (70% identical), guinea pig IFIT3 (63% identical), rat Ifit3 (52% identical), mouse Ifit3b (50% identical), mouse Ifit3 (49% identical), tropical clawed frog ifit5l (31% identical), zebrafish ifit10 (30% identical), tropical clawed frog ifit5 (30% identical), and 7 more. Paralogues in human: IFIT2 (54% identical), IFIT1B (42% identical), IFIT1 (41% identical), IFIT5 (41% identical).
Diseases named in the same sentence as IFIT3 in open-access papers:
IFIT3 is named in the same sentence as 135 diseases in open-access papers, as found by Europe PMC text mining. Sharing a sentence is not in itself a finding about the gene and the disease. The quoted sentences say what the papers report.
viral infection (72 papers, 2011 to 2026). "Specifically, Ifit3-high B cells, which are typically associated with the early immune response to viral infections, are predominantly located in the marginal zone of the lymph node." (PMID 40839713, 2025). "IFIT3 was one of four IFN-induced proteins with tetratricopeptide repeats whose expression was greatly enhanced by viral infection, IFN treatment, and pathogen-associated molecular patterns." (PMID 34367154, 2021). "Likewise, we speculate that the properties defined here underlying the pro-viral function of IFIT3 during influenza virus infection are the same features that allow it to exert antiviral activities during other viral infections." (PMID 40497724, 2025). "The highest ratio in this set was two-fold and out of the top 10 specificities, 7 were in the Type I interferon signature (IFITM3, MX1, IFI6, IFI44L, ISG15, OAS1, IFIT3) and one encodes a protein that is activated by dsRNA as might be present in a viral infection (EIF2AK2)." (PMID 21366908, 2011). "As a key member of the interferon-inducible protein family, IFIT3 is especially critical in the regulation of viral infections and tumor development." (PMID 40061935, 2025). "This demonstrates IFIT3’s broad role in reinforcing the cellular defense mechanisms against viral infections." (PMID 40061935, 2025). "Children with unexplained fever and low CRP had differentially expressed genes linked to interferon-induced immune responses, including IFIT1, IFIT2, and IFIT3, commonly upregulated during viral infections." (PMID 40806258, 2025). "IFIT3 is essential for the proper functioning of the immune response against viral infections and in regulating inflammation in various contexts." (PMID 39305055, 2024). "We selected to study ISG that acted at different levels in the type I/III IFN response to viral infection: IFIT3, IFITM1 and IRF7." (PMID 39664492, 2024). "The viral titers significantly decreased in the supernatant of RIG-I and IFIT3 overexpression sMDCK cells at different time points after viral infection." (PMID 38543921, 2024). "In human viral infection, IFIT3 has roles in interrupting herpesvirus replication, inducing cell cycle arrest through sequestration of Jun activation domain-binding protein 1 (JAB1), or promoting the type 1 IFN response by facilitating protein interactions." (PMID 39162558, 2024). "As the scientific literature suggests a protective role of the IFIT3 gene against other viral infections, it is highly likely that IFIT3 plays a significant role in COVID-19, as indicated by this study." (PMID 39664492, 2024). "Interferon-induced protein with tetratrico-peptide repeats-1(IFIT1) and interferon-induced protein with tetratrico-peptide repeats-3 (IFIT3), both of which play an important role during viral infection, are upregulated in ΔMARCKS IMMs." (PMID 37790394, 2023). "Upon viral infection, IFIT3 expression is up-regulated, which limits the replication of RNA viruses (by direct inhibition of translation); however, IFIT3 has also an indirect antiviral effect through its interaction with MAVS." (PMID 37316325, 2023). "IFIT3 is an IFN-inducible protein whose expression is increased by viral infection and IFN treatment." (PMID 37007947, 2023). "Further, IFIT3 emerged as a potential key regulator of such antiviral functions, as has previously been shown in other immune cells during viral infections." (PMID 37071484, 2023). "Further, IFIT3 emerged as a potential key regulator of such antiviral functions, as it has previously been shown in other immune cells during viral infections 31,32." (PMID 36993474, 2023). "IFI204 and IFIT3 have biological roles in innate immune responses for bacterial and viral infection." (PMID 37007016, 2023). "Intriguingly, upregulated IFIT2 and IFIT3 are also involved in the response to viral infection or immune activation and serve as an essential primary barrier to viral infection." (PMID 35232977, 2022).
viral infection (continued). "CTB 2 cells highly expressed CLU, CFD, and IFIT3, suggesting roles in responding to bacterial or viral infection through the innate arm of the immune system." (PMID 35796428, 2022). "IFIT3 is an interferon-induced protein, also up-regulated with virus infection and double-stranded RNA, capable of inhibiting viral replication and translational initiation, along with cellular migration and proliferation." (PMID 34413772, 2021). "ISG15, IRF7, MX1, RSAD2, and IFIT3 have been found to play a vital role in modulating immune response against the viral infection." (PMID 34631844, 2021). "IFN treatment in HBV patients led to robust IFIT upregulation, while viral infection of liver cells also led to direct IFN-independent IFIT3 upregulation." (PMID 31681236, 2019). "The results also showed that the effect of virus infection-induced cell death appeared 48-72 h after virus infection in cells with knockdown of IFIT3." (PMID 24223959, 2013). "Activating the JAK-STAT1 pathway upon viral infection stimulates IFIT3." (PMID 40936921, 2025). "IFIT3, which is essential during viral infection, was upregulated by PDCoV infection." (PMID 38289117, 2024). "IFIT3, also known as Interferon Induced Protein 3, plays a crucial role as an antiviral protein, with its expression being controlled by different IFNs and viral infections." (PMID 39305055, 2024). "A greater number of genes are upregulated in DCs after MRV infection, many of which are involved in the innate immune response (i.e. Ifit1, Ifit3, Mx1, Gbp2, Oasl1, Isg15, Ccr1, Ifitm2, Oaxl2, Casp1, Casp4) that would be predicted in response to a viral infection." (PMID 38895117, 2024). "Collectively, the expression level of IFIT3 may indicate the immune response to viral infection in B cells, which can be used to compare the immunological memory induced by various vaccination strategies." (PMID 37007947, 2023). "IFIT3 is involved in the innate immune response to viral infection, as it regulates the fusion of the virus to endocytic vesicles and inhibits virus membrane fusion, in order to prevent the release of viral particles into the cytoplasm and control viral spread." (PMID 36679948, 2023). "With regard to the relationship between IFIT3 and viral infection, IFIT3 was found to be differentially expressed in response to infection with RNA viruses and was considered to have predictive potential for COVID-19 because the expression level can be affected by SARS-CoV-2 infection." (PMID 37007947, 2023). "Furthermore, viral infection increased the mRNA expression of cytokines (Il6, Tnf), chemokines (Cxcl10, Ccl2), and interferon-responsive genes (Ifnb1, Ifit3, Irf7, Gbp5 and Isg15)." (PMID 37081549, 2023). "Induction of IFIT2 and IFIT3 were observed in hNECs across both lineage infection groups with the strongest signal observed in B/Yamagata-infected cells for IFIT2 with similar amounts of protein detected across all virus infections for IFIT3." (PMID 37766362, 2023). "The IFIT3 gene has been described as a protective molecule against virus infection." (PMID 35746439, 2022). "IFIT3 was highly upregulated in a human thyroid follicle culture system upon stimulation with a chemical analog of viral double-stranded RNA (dsRNA) to mimic viral infection." (PMID 33794925, 2021). "The increased expression of dsRNA receptor TLR3 and IFN induced genes ISG56, ISG43, Mx1 and IFIT3 after stimulation with poly I:C mimicking a viral infection indicates that these cell lines can be used as effective in vitro models to study the bat's innate immune responses to virus infection." (PMID 25295526, 2014). "While IFITs play a central role in regulating the replication of diverse viral infections, IAV exploits the antiviral activity of both IFIT2 and IFIT3 to enhance replication." (PMID 40497724, 2025). "Once inside the cells, it interacts with transcription factors and modulates the activity of genes like IFIT3 and STAT1 which are vital for responding to viral infections." (PMID 40936921, 2025).
viral infection (continued). "The observed elevation of ISGs, encompassing ISG15, IFI6, IFIT1, IFIT2, IFIT3, IFI44L, and IFITM3, highlights SARS-CoV-2’s ability to activate the host’s interferon response—a critical defence mechanism against viral infection." (PMID 39940816, 2025). "Previous studies of viral infections have revealed the existence of IFNAR-independent pathways mediating the expression of ISGs, such as IFIT1, IFIT2, IFIT3 and ISG15, all of which were expressed by FVB/N macrophages during priming with M. ulcerans antigens." (PMID 37428812, 2023). "Our study has established that in the white matter of untreated HAND subjects, the expression of STAT1, IFIT3, and ISG15 was upregulated as expected due to viral infection." (PMID 36841839, 2023). "Long-range signaling of IFN released from infected neurons at the OB after viral infection of the nasal mucosa upregulated the expression of ISGs (IFIT2, IFIT3, OAS, and MX1) in uninfected brain regions." (PMID 36325336, 2022). "We next used the viral mimetic poly I:C to experimentally model viral infection in U251 astrocytoma cells and evaluated the role of RP5-998N21.4 in the response to infection mediated through upregulation of IFIT3 expression." (PMID 35232977, 2022). "We extended our analysis to a range of ISGs that have previously been identified as being regulated directly by virus infection in an IFN-independent manner i.e., IFIT1, IFIT2, IFIT3, ISG15, CXCL10, Mx1 and Mx2." (PMID 30871003, 2019). "Infected cultures also displayed upregulation of viral infection markers IFN-beta, IFIT3, and CXCL10." (PMID 31875556, 2019). "The IFIT family includes four canonical human members (IFIT1, IFIT2, IFIT3, and IFIT5) and three mouse members (IFIT1, IFIT2, and IFIT3), which are induced upon simulation with IFN, virus infection, or other PAMP recognition." (PMID 24653722, 2014). "IFIT-1, IFIT-2, IFIT-3, and IFIT-5, which were found to be the most down-regulated genes in LBW newborns, are induced in response to type I and type II IFNs against viral infections." (PMID 23626859, 2013). "Selected antiviral genes (IFI6, IFIT3 and IFITM3) were also up-regulated, indicating that PAMs were attempting to control the viral infection." (PMID 23527143, 2013). "We found 12 downregulated genes involved in immune response and the immune response to virus infection, and interestingly, they were mainly related to the interferon family of anti-viral factors, such as IFIT1, IFIT3, and OASL." (PMID 22455445, 2012). "Given that the interferon response is central to the innate immune system's defense against viral infections, we tested whether Herpes Simplex Virus type 2 (HSV‐2) infection could increase Ifit3 expression in cluster 4 SGCs." (PMID 41134052, 2026). "Interferon induced protein with tetratricopeptide repeats 3 (IFIT3) and interferon induced protein with tetratricopeptide repeats 2 (IFIT2) are both members of IFITs and are highly expressed in the innate immune response of cells to viral infection." (PMID 35187081, 2022). "Both IFIT3 and MDA5 have RNA-binding properties, and are involved in responses against DNA and RNA virus infection, suggesting that HESN PBMCs are more ready to detect RNA or DNA viral infection." (PMID 35336878, 2022). "We observed that adult patients with epileptic seizures had peripheral whole blood that included miR-654-3p, miR-323a-3p, miR-323b, miR-3283p, miR-342-5p, miR-150-5p, miR-3395p and IFIT3, IFIT1, IFI44L, OAS3, and LY6E in the pathways connected to viral infection." (PMID 36172025, 2022). "Our results confirm and extend these observations by showing that the forced expression of IFIT1, IFIT2 or IFIT3 in human fibroblasts completely inhibited the replication of CHIKV and that the individual knock-down of each of these genes facilitated viral infection." (PMID 30959732, 2019).
viral infection (continued). "Notably, following viral infection, the levels of these transcripts (with the exception of EGR1) decreased at 1 dpi, with the levels of IFIT3 and ISG15 remaining significantly depleted at 3 dpi." (PMID 31451757, 2019). "IFIT (IFN-induced protein with tetratricopeptide repeats (TPRs))-family proteins contain four members in humans, namely IFIT1 (ISG56), IFIT2 (ISG54), IFIT3 (ISG60) and IFIT5 (ISG58), and are induced to high levels in response to IFN signaling and/or viral infections." (PMID 29215570, 2017). "Our PCR analysis of IFIT3 gene expression revealed significant upregulation in the HIV-infected group compared to the control group, which was almost 7-fold greater than the control group (p< 0.0001), indicating a notable response to viral infection at the genetic level." (PMID 40936921, 2025). "Importantly, the feIFN-ω’ can effectively promote the expression of antiviral proteins IFIT3, ISG15, Mx1, and ISG56, and further enhance host defense to eliminate FPV infection in vivo, suggesting a potential candidate for the development of therapeutic agent against feline viral diseases." (PMID 35068319, 2022).
COVID-19 (32 papers, 2020 to 2025). A disease caused by infection with severe acute respiratory syndrome coronavirus 2. "Our results suggest a potential emerging role of the ISG interferon-inducible protein with tetrapeptide repeats 3 (IFIT3) gene in the protective immunity against symptomatic COVID-19." (PMID 39664492, 2024). "Important gene combinations in the white blood cells of patients with COVID-19, including IFIT3, OASL, USP18, XAF1, IFI27, and EPSTI1, can be used for its diagnosis." (PMID 35928229, 2022). "In our study, we report that IRF7, ISG15, IFI44L, IFIT1, and IFIT3 gene expression is increased in CD16+ monocytes from people with mild COVID-19 compared to healthy controls." (PMID 34108966, 2021). "Remarkably, we found a significant upregulation of the ISG interferon-inducible protein with tetrapeptide repeats 3 (IFIT3) gene exclusively in exposed uninfected or asymptomatic females, suggesting a potential role in protective immunity against symptomatic COVID-19." (PMID 39664492, 2024). "In addition, IFI30 was specifically upregulated in monocytes during HIV-1 infection, whereas SLAMF7 and IFIT3 were upregulated in plasmablasts and T cells from COVID-19 patients respectively." (PMID 36992700, 2023). "IFIT3 could be related to immune response to SARS-CoV-2 infection based on the findings of several studies, demonstrating that IFIT3 is strongly expressed in the pulmonary inflammatory cells of patients with COVID-19." (PMID 37007947, 2023). "In particular, in the patient with COVID-19 and HD the expressions of the CD38 and of the IFIT3 genes are strongly increased, while in the patient with COVID-19 and CLL they are both normally expressed at a level comparable to that observed in the COVID-19 patients without the Low T3 syndrome." (PMID 33794925, 2021). "Furthermore, the transcriptome-wide analysis identified six novel loci, among others, consisting of genes—IFIT3, KEAP1, and GNL3 demonstrating their putative association with COVID-19 hospitalization outcome." (PMID 34315903, 2021). "The top enriched clusters across SARS-CoV-2/COVID-19 studies included genes OAS1-3, IFIT3, SAMHD1, and MX1 involved in the innate immune response, interferon signaling, and defense response to the virus." (PMID 41227320, 2025). "In this study, the highest differentially expressed genes in COVID-19 (+) tissue, including ISG15 itself, IFIT1, RSAD2, OAS1, MX1, OASL, and IFIT3, are all important for the ISG15 pathway’s progression and are part of the lung tissue’s antiviral response." (PMID 38932146, 2024). "Specifically, in COVID-19, these genes were CD52, ISG15, and MMP9; in influenza, they included IFI44L, IFIT3, ISG15, and OAS1; and in HIV, OAS1 was identified." (PMID 38601162, 2024). "As an indication of disease severity, we measured the mRNA expression levels of IFN-stimulated genes (IFIT1, IFIT3, ISG15, and MX2), pro-inflammatory cytokines (IL6, IL10), and chemokines (CXCL10, CCL2) that are correlated with COVID-19 exacerbation." (PMID 35562337, 2022). "In large airway tissues, genes related to the mucosal layer (MUC4, MUC5AC, MUC5B) as well as cytokine-mediated signaling pathway genes (CCL20, CXCL1, CXCL6, CXCL6, MMP1) and type I interferon genes (IFIT3, ISG15, STAT1, MX1) were upregulated in COVID-19." (PMID 35233546, 2022). "Comparison of severe and mild Symptomatic COVID-19 cases revealed an upregulation of CD177, the neutrophil marker, CXCL16, MAPKMAPK2 and IRF2BP2 with downregulation of ISGs; IFIT, IFIT3, OAS1, OAS2, LY6E and MX1 in severe cases." (PMID 34824360, 2021). "Another study also reported increased interferon signaling genes including IFI44L, IFIT1, IFIT3 and ISG15, in CD16+ monocytes in COVID-19 cases compared to healthy controls." (PMID 34108966, 2021). "OAS1, OAS2, OAS3, IFIT1, IFIT3, IFI44, IFI44L and IFITM1: Current COVID-19 genetic studies incline to analyze those genes together." (PMID 34109284, 2021).